ZFYVE21 (zinc finger FYVE-type containing 21)
Description:
Plays a role in cell adhesion, and thereby in cell motility which requires repeated formation and disassembly of focal adhesions. Regulates microtubule-induced PTK2/FAK1 dephosphorylation, an event important for focal adhesion disassembly, as well as integrin beta-1/ITGB1 cell surface expression.
Synonyms: ZF21; MGC2550; HCVP7TP1
Tractability: PROTAC: ubiquitination databases record sites on it; its protein half-life has been measured.
Gene: Protein-coding gene on chromosome 14 (103,715,730 to 103,733,669, forward strand). Ensembl gene ENSG00000100711.
Subcellular location: Cell junction, focal adhesion; Cytoplasmic vesicle; Endosome
Gene Ontology:
Molecular function: protein binding; metal ion binding
Cellular component: cytoplasmic vesicle; endosome; focal adhesion
Genetic constraint (gnomAD): Loss-of-function variants: 21 observed, 28.05 expected, observed/expected ratio (o/e) 0.75, 90% interval 0.53 to 1.08. The upper end of that interval is the gene's LOEUF score, 1.08, which puts it in group 4 of 6, group 1 being the genes least tolerant of losing a copy. Missense variants: 326 observed, 305.73 expected, observed/expected ratio (o/e) 1.07, 90% interval 0.97 to 1.17. Synonymous variants: 151 observed, 122.63 expected, observed/expected ratio (o/e) 1.23, 90% interval 1.08 to 1.41.
Homologues: Orthologues: chimpanzee ZFYVE21 (99% identical), macaque ZFYVE21 (97% identical), dog ZFYVE21 (88% identical), pig ZFYVE21 (86% identical), mouse Zfyve21 (85% identical), rat Zfyve21 (84% identical), guinea pig ZFYVE21 (82% identical), tropical clawed frog zfyve21 (70% identical), zebrafish zfyve21 (70% identical).
Diseases named in the same sentence as ZFYVE21 in open-access papers:
ZFYVE21 is named in the same sentence as 12 diseases in open-access papers, as found by Europe PMC text mining. Sharing a sentence is not in itself a finding about the gene and the disease. The quoted sentences say what the papers report.
schizophrenia (2 papers, 2021 to 2022). A major psychotic disorder characterized by abnormalities in the perception or expression of reality. "CpGs selected by CEWAS include cg06985993 and cg08213375 for YPEL3 and ZFYVE21, respectively, whose DNAm levels are associated with schizophrenia GWAS SNPs: rs3814877 and rs4900597." (PMID 34807913, 2021). "Whereas the most significant gene observed in the CUD and schizophrenia meta-analysis was ST3GAL3 (P = 9.68 × 10−16) and in the ND and schizophrenia meta-analysis the gene ZFYVE21 (P = 1.11 × 10−14)." (PMID 36151087, 2022). "As an example, YPEL3 and ZFYVE21 are significant for schizophrenia based on CEWAS but p>0.05 based on MetaXcan." (PMID 34807913, 2021).
breast carcinoma (1 paper, 2020). "In a breast cancer patient whose status changed from SD to PD, the ctDNA content of most mutations increased, but the level of ZFYVE21, a known breast cancer marker, continued to decrease." (PMID 32738923, 2020).
COVID-19 (1 paper, 2022). A disease caused by infection with severe acute respiratory syndrome coronavirus 2. "In addition, using the ratio test to perform a causal analysis, we detected a potential causal link from a genetic predisposition for vitamin D deficiency to the severity of COVID-19, mediated by the ZFYVE21 gene." (PMID 36156592, 2022). "We found that Vitamin D carries two interesting hits suggesting causal pathways from Vitamin D concentration to the severity of COVID-19, namely, the genes KLC1 and ZFYVE21." (PMID 36156592, 2022).
head and neck cancer (1 paper, 2017). A primary or metastatic malignant neoplasm affecting the head and neck. "One of these genes, ACVRL1 correlated with tumour progression in patients with head and neck cancers; whereas two other genes: ZFYVE21, and CLEC3B were related to cancer invasiveness." (PMID 28574441, 2017).
Infertility (1 paper, 2021). "Of interest, some candidates related to sperm and infertility were identified, containing MORC1, TDRD9, ZFYVE21, ADGRB3, SPAG17, CKB, and WDR3, which may have effects on sperm motility and fertilization." (PMID 33477586, 2021).
insomnia (1 paper, 2025). A sleep disorder characterized by difficulty in falling asleep and/or remaining asleep. "Finally, SNPs in the genetic region of chromosome 14 near genes PPP1R13B, ZFYVE21 and LINC00637 have been previously associated with smoking, risk taking, problematic alcohol use, number of sexual partners, sex hormone-binding levels, BIP, SZC and insomnia." (PMID 39975919, 2025).
osteoarthritis (1 paper, 2019). A noninflammatory degenerative joint disease occurring chiefly in older persons, characterized by degeneration of the articular cartilage, hypertrophy of bone at the margins and changes in the synovial membrane. "We next examined synovium from patients with either high- or low-titer anti-rheumatoid factor antibody rheumatoid arthritis (RA) or osteoarthritis (OA) for NIK, ZFYVE21, and MAC (polyC9)." (PMID 31113953, 2019).
ZFYVE21 also shares sentences with these, for which no sentence is quoted: tumor (3 papers); cancer (2); rheumatoid arthritis (1); SLE nephritis (1); vitamin D deficiency (1).